CCL5 (C-C motif chemokine ligand 5)
Diseases named in the same sentence as CCL5 in open-access papers (continued):
Sharing a sentence is not in itself a finding about the gene and the disease.
tumor (continued). "We first confirmed that tumor tissues with chemohormonal treatment showed a higher level of IFN-stimulated genes, such as IFIT1, IFI44, CCL5, and IFNB, compared with treatment-naive tissues." (PMID 35836810, 2022). "This possibility is highly supported by the fact that joint inhibition of CXCR1/2, CCR2 and CCR5 led to complete inhibition of tumor cell invasion and of CCL2 and CCL5 production." (PMID 35205789, 2022). "Radiation also increases production of CCL5, which acts to recruit pro-inflammatory CCL2+CCL5+ macrophages both inside the tumour and in the peripheral circulation." (PMID 33499003, 2021). "We found that the level of C-C motif chemokine ligand 5 (CCL5), a chemokine critical for CD8+ T cell homing in tumor regions, was significantly decreased in tumors with circIGF2BP3 overexpression, as determined by qPCR." (PMID 34416901, 2021). "CCL5 (RANTES), which is recognized by CCR1, CCR3, and CCR5, plays important roles in the recruitment of monocytes to tumor sites." (PMID 34572013, 2021). "A complex network of interactions occurs between CCL5 and CCR5 in GBM including GBM cells, GSCs, and the GME cellular components of the tumor tissue." (PMID 33923334, 2021). "IFN-γ induces both CXCL10 and CCL5, and both chemokines showed a strong positive correlation with CD8 T cell infiltration into tumours." (PMID 33925140, 2021). "While baseline IFNg is higher in the recurrent tumor, the level of TNFa, RANTES (CCL5), IP-10, IL-5, IL-10, MIP1a (CCL3), MIP1b (CCL4), and GM-CSF are all significantly lower in the recurrent tumor." (PMID 34221953, 2021). "These genes included C–C chemokine ligand 5 (CCL5) and C–C chemokine ligand 22 (CCL22) which have been shown to attract suppressive immune cells to tumours." (PMID 34602068, 2021). "CAR-T cells commonly express receptors RANTES receptors, such as CCR1, CCR3, and CCR5, and combined use of CCL5-expressing oncolytic virus with engineered CAR T cells powerfully promoted the viability and tumor clearance in some of the preclinical studies." (PMID 33494834, 2021). "CCR5, expressed on MDSC, TAMs, and Treg cells, plays a central role in the chemotaxis of MDSC into the tumor microenvironment via the ligands CCL3, CCL4, and CCL5." (PMID 35127700, 2021). "CCL5 and its receptors CCR1 and CCR5 are key players that induce microglia migration to the tumour site and subsequent changes in phenotype." (PMID 33803414, 2021). "Coincidentally, we also showed that the expressions of CCL5 and CCL20 were appreciably increased in HCC tumor tissues compared to adjacent tissues by immunohistochemistry." (PMID 34938730, 2021). "The previous study reported that chemokines like CCL5 and CXCL10 can modulate tumor sensitive to immunotherapy." (PMID 33898414, 2021). "This is in line with reports that identified CCR2 ligand CCL2 and CCR5 ligand CCL5 as the main factors, driving M-MDSC migration to the tumor in vivo." (PMID 33578808, 2021). "Neutrophils which exist in tumor microenvironment are capable of producing angiogenic chemokines and cytokines including CCL2,CCL3, CCL5, CCL10, IL4 and IL10 to promote tumor growth, invasion and angiogenesis." (PMID 34123808, 2021). "Our data also indicate a strong positive correlation between CCL5 and CD4+ T cell abundance in tumours." (PMID 33925140, 2021). "Other chemokines known to regulate tumor development and progression include the CCR5 receptor ligands CCL3, CCL4, and CCL5." (PMID 33406733, 2021). "As for the CCR2 axis, the CCR5 axis is not only related to Treg recruitment, because its ligands (CCL3, CCL4, CCL5 and CCL8) are also involved in tumor progression and metastases." (PMID 33924428, 2021). "We identified multiple tumor-immune interactions, for example between CXCR3, CCL5, TNFRSF1B, and VCAM1-expressing malignant T cells and macrophages/fibroblasts positive for CXCL9, CCR1, GRN, and IGTB1, respectively." (PMID 33816243, 2021).
tumor (continued). "The treatment of cold tumors with Vps34 inhibitors induces the release of inflammatory chemokines such as CCL5 and CXCL10 in tumor cells, resulting in homing of natural killer (NK) and CD8+ T cells to the tumor microenvironment." (PMID 34680466, 2021). "Vaccination enhanced the expression of CCR5+ IFN-γ+ and CXCR3+IFN-γ+ on CD8+ T cells, which led to a significant increase in CCL5 and CXCL9/10 secretion from irradiated tumor cells." (PMID 33469123, 2021). "In the TME, the presence of CAFs and their secretion of chemokines and cytokines such as CCL2, CCL5, CCL17, IL-1, IL-6, IL-13, and IL-26 can favor a tumor-promoting Th2 and Th17 immune response, at the expense of tumor-protective Th1 responses." (PMID 34663337, 2021). "Expression array analysis revealed that both baseline and tumor cell-induced expression of the chemokines CCL3, CCL4, and CCL5 were markedly reduced in MEKK1−/− mammary fibroblasts." (PMID 33868996, 2021). "TAMs constitute one of the most abundant populations of PDAC, and can derive from the differentiation of monocytes recruited by tumor-produced CCL2 and CCL5, or from embryonic precursors." (PMID 33802061, 2021). "Monocytes/macrophages are actively recruited by tumor cells that produce chemokines such as CSF-1, monocyte chemoattractant protein-1 (MCP-1/CCL2), and CCL5." (PMID 34572013, 2021). "In animal models, NK cells can induce chemokine (C-C motif) ligand 5 (CCL5) and lymphotactin (XCL1) and recruit cDC1 to the tumor microenvironment; however, tumoral prostaglandin E2 (PGE2) can inhibit this anti-tumoral positive loop." (PMID 33692796, 2021). "NK cells promoted immune control of tumours by upping the intensity of the orthodox type-1 dendritic cells (cDC1s) in tumours via two cytokines'—FLT3LG and CCL-5—production, as per recent studies." (PMID 34336101, 2021). "The M-MDSC is attracted to tumor sites by CCL2, CCL5, and CSF1 and PMN-MDSC was attracted by CXCL1, CXCL5, CXCL6, CXCL8, and CXCL12." (PMID 34858479, 2021). "In fact, TAM and osteoclasts are recruited by tumor-derived inflammatory cytokines and chemokines (TNF-α, CCL2, CCL5) upon EMT activation and during metastatic outgrowth." (PMID 34064859, 2021). "Heightened dual expression of the ligands for CCR5 and CXCR3 (CCL5 and CXCL9, respectively) positively correlates with the amount of tumor CD8a transcripts and patient survival in cancers of the ovary, breast, lung, colon, as well as melanoma." (PMID 34354714, 2021). "In regulatory T (Treg) cells isolated from tumor-draining lymph nodes of mice harboring CT26 (colon carcinoma cell) tumors, CCL5 treatment enhances Treg cell-mediated CD8+ T cell apoptosis." (PMID 34503214, 2021). "In this study, we further verified that CCL5 and CCL20 were significantly upregulated in both HCC cell lines and tumor tissues compared with normal controls by Western blot and IHC, which were consistent with the transcriptional levels." (PMID 34938730, 2021). "Many pre-clinical models have shown that eosinophils play a vital role in the tumor microenvironment (TME) and response to immunotherapy through increased expression of CCL5, CXCL9, and CXCL10." (PMID 34732251, 2021). "MSCs promptly migrate into tumor sites in response to chemokines, such as CCL2, CCL5, CXCL12, and CXCL16, and are expanded by cytokines, such as TGFβ, VEGF, FGF, and IGF, all of which are released from the tumor milieu." (PMID 33535613, 2021). "Monocytic-MDSCs express CCR2 and CCR1/CCR5, and can be recruited into tumor tissues by CC chemokines such as CCL2 and CCL5, respectively." (PMID 34885241, 2021). "Targeting the CCR5/CCL5 axis with MVC reprograms immunosuppressive M2-TAMs to anti-tumoural M1-TAMs, reinvigorating anti-tumour immunity." (PMID 34638423, 2021). "Further, CCL5 and its receptor CCR5 are required for productive anti-tumor responses following immunotherapy." (PMID 34030676, 2021).
tumor (continued). "Enhanced NF-κB activity leads to tumor rejection and suppresses tumor growth via upregulating the expression of several T cell chemokines, including CCL2, CCL5, and recruiting cytotoxic CD8 T cells." (PMID 34277453, 2021). "Tumor-conditioned monocytes presented similarities with ncMO phenotype from DLBCL and were prone to migrate in response to CCL5 and CXCL12, and presented similarities with DLBCL-infiltrated myeloid cells, as defined by mass cytometry." (PMID 34975843, 2021). "The link between the CCL5/CCR5 pathway and tumour growth is also evident in vivo, as knockdown of CCR5 in tumour cells can significantly reduce tumour size and expression of the proliferation marker Ki67." (PMID 33803414, 2021). "The expression of CCL5 in CD146+ pericytes and tumor recurrence status of two representative isocitrate dehydrogenase (IDH)-wild-type GBM patients (Case 1: CCL5high/CD146high and Case 2: CCL5low/CD146low) were assessed." (PMID 34239070, 2021). "Such infiltration resulted from the induction of STAT1 and IRF7, and the expression and secretion of pro-inflammatory chemokines and cytokines (CCL5, CXCL10, and interferon-γ) in tumor cells in vitro and tumor plasma in vivo." (PMID 34681622, 2021). "In comparison with adjacent and precancerous tissues, we found a significant reduction of CD40+, CD27+, KLRB1+, and CCL5+ B cells (clusters 4, 9, 1, and 3, respectively) and MZB1+, DUSP1+, and CCL3+ plasma cells (clusters 5, 7, and 8) in tumor tissues." (PMID 34185431, 2021). "TAMs are mainly recruited from the periphery by chemokines released from tumor tissues, including CCL2, CCL3, CCL4, CCL5 and CXCL12." (PMID 34925375, 2021). "The CC chemokine, CCL5 (also known as RANTES), is a downstream target of the NF-κB pathway known to promote tumor cell proliferation, invasion, and angiogenesis by facilitating the recruitment of eosinophils, monocytes, T cells, and basophils." (PMID 33390169, 2021). "In our samples, the mRNA levels of CCL5, FASLG, EOMES, and PDCD1 in tumor tissues were significantly higher than those in normal tissues." (PMID 34531849, 2021). "Owing to the crucial role of CCL5 and CCL25 in TIME, we analyzed the immune cell profiles in TNBC to explore the link between IRGPI and tumor-immune cell compositions." (PMID 34771505, 2021). "With the expression of both CCL5 and its receptor CCR5, tumour cells can use the autocrine signalling circuit to regulate their own proliferation, through activation of the phosphoinositide 3-kinase (PI3K)/AKT pathway." (PMID 33803414, 2021). "Tumor-conditioned monocyte shown an increased migration in response to CXCL5, CXCL12, CCL3, and CCL5." (PMID 34975843, 2021). "DTYMK promoted the expression of CCL5 by affecting NF-κB, which led to increased infiltration of CD163+ M2-type TAMs in the tumor microenvironment." (PMID 34795209, 2021). "MDSCs are recruited from the bone marrow to the tumour site via cancer cell-derived chemokines such as CCL2, CCL5, CXCL5, and IL-854." (PMID 33659922, 2021). "In malignancies, several chemokines, including CCL5, CCL27 and CX3CL1, can be produced by tumor cells, which in turn contributes to the recruitment of NK cells." (PMID 33802954, 2021). "Activated NK cells secrete several chemokines, such as CCL4, CCL5 and XCL1, that are responsible for the recruitment into the tumor of CCR5- and XCR1-expressing cDC1s." (PMID 34975880, 2021). "In the second loop, CCL5 secreted from MSCs activates BCCs via CCR5, which promotes the BCCs to secret CSF1 and further recruits TAMs and MDSCs to the tumor region." (PMID 33849537, 2021). "Another chemokine called chemokine C-C motif ligand 5 (CCL5) is expressed by many cell types such as immune cells, epithelial cells, fibroblasts, and more importantly, by tumor cells." (PMID 34638560, 2021).
tumor (continued). "CCL5 is secreted by T cells, Platelets, Macrophages, Endothelial cells, and Fibroblasts and stimulates the migration of T cells and monocytes to drive apoptosis of tumor-infiltrating T cells; therefore, it was found that reducing the expression of CCL5 may have a beneficial effect on various tumors." (PMID 34777462, 2021). "Herein, we describe one tumor node consisting of the C–C chemokine receptor 5 (CCR5) and its ligands (such as CCL5) of which inhibition prevents cancer progression." (PMID 33923334, 2021). "While promoting tumour EMT and metastasis, unceasing inflammatory responses can also influence restrained cancer growth, involving CCL-5 in human NSCLC samples, said the study." (PMID 34336101, 2021). "Endothelial cells from different sources were mixed and assigned to four cell types, including immune EDCs (CCL5 and CXCL13), lymphatic EDCs (PDPN and PROX1), tumor EDCs (ACKR1 and POSTN), and vascular EDCs (PLVAP and SLC9A3R2)." (PMID 34697289, 2021). "Six1 overexpression in MC38 recruits TAMs by increasing the expression of macrophage-specific colony stimulating factors CCL2 and CCL5, further promoting the growth and metastasis of CRC and remodeling the tumor matrix." (PMID 34445193, 2021). "The expression levels of CCL5, CD3E, and LCK were lower in tumor tissues samples than those in adjacent non-tumor tissue samples, which is consistent with the results of transcriptomics." (PMID 34218795, 2021). "Strikingly, a large proportion of the IFNγ signature genes were upregulated by SHP2 inhibition specifically in tumor cells in co-culture, including cytokines (CXCL9, CXCL10, CXCL11 and CCL5) and antigen presenting machinery (HLA-A, HLA-B and B2M)." (PMID 33446805, 2021). "Chemokine levels of CCL5 and CXCL10 were remarkably increased in supernatants of tumor tissues after combined incubation with curcumin and PIC." (PMID 33809574, 2021). "Tumor cell migration to metastatic lesions is promoted through MSC secretion of chemoattractants, such as CXCL1, CCL5, CXCL5, CXCL8 and CXCL7." (PMID 33472580, 2021). "Strong positive-correlations (r > 0.5, p < 0.05) were observed between the expression of CXCL10 and CCL5 and CD8+ T cell abundance in tumours, while CCL17 and CCL22 were negatively correlated (r < −0.5, p < 0.05) with CD8+ T cell infiltration." (PMID 33925140, 2021). "Oncolytic adenovirus armed with the chemokine RANTES (CCL5) to promote infiltration, as well as the cytokine IL15 to support T cell survival once in the tumour conferred enhanced therapeutic benefit when used in combination with GD2 CAR T." (PMID 33807553, 2021). "Together with CCL5, CXCL10 is a key player in driving NK cells and CD8+ T cells into the tumour bed." (PMID 33801414, 2021). "CCL5 and MMP expression is increased in mechanosensing osteocytes as a consequence of increased tumor burden and intraosseous pressure, thus facilitating PrCa growth and invasion." (PMID 34064859, 2021). "In orthotopic but not subcutaneous mouse models, IL-33 activates ILC2s, which in turn produce CCL5 to recruit CD103+ cDC1s to the TME which then prime and activate CD8 T cells to infiltrate the tumor and exert an anti-tumor immune response." (PMID 33584701, 2020). "We next investigated if tumor-secreted BMP7 regulates IL1A, IL1B, TNF, and CCL5 via MAPK14 in macrophages." (PMID 32973129, 2020). "This profile includes XCL1, mainly secreted by tumor resident CD56low NK cells, and CCL4 and CCL5 mostly produced by CD56low and CD56high NK cells and CD8+ T cells." (PMID 33679726, 2020). "In mouse models of CRC, the knockdown of tumor cell CCL5 and the blockade of CCR5 signaling decreased Treg infiltration and apoptosis of tumor-infiltrating CD8+ T cells and reduced tumor growth." (PMID 32630699, 2020). "It was shown that the chemokine CCL5 and its receptor CCR5 play the important roles in GBM development and tumor invasion." (PMID 32456359, 2020).
tumor (continued). "Tumor cells-macrophage co-culture increases expression of IL10, IL12, IL6, TNF, CCL5, CCL22, and CSF1 in macrophages, thereby inducing M2-like polarization." (PMID 32219066, 2020). "It has also been demonstrated that MDSC arising from the bone marrow are recruited to the tumor through blood circulation, and that tumor infiltrating M-MDSC mediate the recruitment of Treg in tumor-bearing mice via CCL4 and CCL5 production." (PMID 33603754, 2020). "In vivo, robust CCL5 production in LCMV infected Ma-Mel-86a tumor bearing mice led to recruitment of NK cells and fast tumor regression." (PMID 32973762, 2020). "It is worth noting that the expression of RKIP in tumor cells is decreased in TNBC, which leads to the increase of CCL5 secretion to promote the recruitment of macrophages, thus enhancing the invasion of tumors." (PMID 33224886, 2020). "MDSCs are mobilized from the bone marrow and recruited into the primary tumor site through various chemo-attractant factors such as M-CSF, GM-CSF, CCL-2 (MCP-1), CCL-5 (RANTES), Bv8, which are particularly secreted in hypoxic regions of the tumor." (PMID 32580431, 2020). "Our previous study found that improved survival upon genetic loss of Erk5 in PtenΔ/Δ PCa model was related to increased levels of the T cell recruiting cytokines Ccl5 and Cxcl10 and enhanced T cell infiltration (predominantly CD4+) within the tumours." (PMID 31740786, 2020). "The chemokine CCL5/RANTES is a versatile inflammatory mediator, which interacts with the receptor CCR5, promoting cancer cell interactions within the tumor microenvironment." (PMID 32545571, 2020). "The fold changes of CCL5 and CXCL9 were more than 2.5-fold higher in tumor tissues than the levels in normal tissues." (PMID 32081834, 2020). "The increased expression of CCL5 activates CCR5 and ultimately results in tumour progression by means of increased cancer cell proliferation, while the elimination of tumours by CD8+ T-cells is inhibited." (PMID 32098198, 2020). "CCL5 and CCR5 are constitutively expressed by cHL-derived cell lines and by tumor cells from cHL tissues." (PMID 32630699, 2020). "Although blood and tumor-infiltrating NK cells express predominantly perforin and granzyme genes that are related to cytotoxicity, tumor-infiltrating NK cells upregulate XCL1, XCL2, CCL3, CCL4, CCL4L2, and CCL5 that are chemokine genes." (PMID 33424862, 2020). "Macrophages are attracted to tumor sites expressing chemotactic factors such as CCL2, CCL5, CCL7, CCL8, CXCL1, and CXCL12." (PMID 31991604, 2020). "High levels of intra-tumoral chemokines such as CCL5, CXCL9, CXCL10 enhance the recruitment of T-cells into the tumor and preclinical studies in mice showed that infiltrating anti-tumor CD8+ T-cells are required for clinical response to anti-PD-1 treatment." (PMID 35582440, 2020). "Measurements of 36 different chemokines in the culture medium revealed a significant decrease in the secretion of CCL5, CCL8, CXCL1, CXCL2, CXCL5, and TGFβ1 and a significant increase in TGFβ2 secretion by TB9-Fhit transfected tumor cells." (PMID 32545680, 2020). "IL-33–activated ILC2 enhances DCs migration into cancer tissues via C-C motif chemokine ligand 5 (CCL5) and further improve CD8+ T cell-mediated tumor immunity." (PMID 33193374, 2020). "NKs also release cytokines and chemokines including IFN-γ, TNF-α, GM-CSF, MIP1-α, RANTES, IL-6, and CCL5 thus attracting and activating monocytes, macrophage, T cells, DCs, and neutrophils to promote an anti-tumor response." (PMID 32457760, 2020). "Mechanistically, cancer-FOXP3 directly transactivates CCL5, and the CCL5-CCR5 axis promotes Treg cell accumulation in tumor lesions from peripheral blood in vitro and in vivo." (PMID 32425930, 2020). "CCL5 increases tumor growth by activating STAT5 and cyclin D1 pathways, enhanced tumor invasion and synergizes with IL-6." (PMID 32630699, 2020).